INS (insulin)
Diseases named in the same sentence as INS in open-access papers (continued):
Sharing a sentence is not in itself a finding about the gene and the disease.
metabolic syndrome (continued). "The special strengths of the present study are worth emphasizing: only individuals without any clinical features of the metabolic syndrome took part in the study, which therefore allows us to investigate the role of insulin sensitivity per se on cIMT." (PMID 23185996, 2012). "The existence of metabolic syndrome (MetS) implies a shift from a pathophysiology concept based on metabolic abnormalities resulting from an insulin-resistant state to an epidemiological construct based on abdominal obesity and crude correlates of the features of insulin resistance." (PMID 23245314, 2012). "More particularly, we find that berberine can improve insulin sensitivity by adjusting adipokine secretion both in primarily cultured preadipocytes as well as in metabolic syndrome patients, and this was not well characterized in previous human studies." (PMID 22474499, 2012). "C‐peptide levels (AUC=0.62) had significantly higher AUC's compared with fasting plasma glucose levels (AUC=0.56), HOMA‐IR index (AUC=0.58), fasting serum insulin levels (AUC=0.57), QUICKI index (AUC=0.42), and metabolic syndrome (AUC=0.56) for cardiovascular death, with P values at <0.001." (PMID 23316320, 2012). "Encapsulated fruit and vegetable juice powder concentrates did not alter insulin or glucose measures in this sample of adults with metabolic syndrome." (PMID 21714890, 2011). "The prevalence of metabolic syndrome was about three times higher for men and over two times higher for women in the insulin-resistant subjects compared to the non-insulin-resistant subjects." (PMID 22025967, 2011). "Second, it has been shown that metabolic parameters such as fasting glucose are not the primary predictors of the metabolic syndrome and that insulin sensitivity can already be substantially decreased within the normal range of fasting and 2-hour glucose." (PMID 20721358, 2010). "Adjusting for the separate components of the metabolic syndrome (fasting serum HDL, triglycerides or insulin, fasting blood glucose, waist girth and blood pressure) did not alter the association of moderate-to vigorous or vigorous LTPA with hopelessness either." (PMID 19555509, 2009). "In case of a syndrome, such as the “metabolic syndrome”, in a properly designed ontology the articles retrieved will contain symptoms and other characteristics for it (e.g. type II diabetes, hypertension, insulin resistant, low HDL, hypertension, all of them being parts of the metabolic syndrome)." (PMID 18460175, 2008). "Correlation analysis of any CAMs with postprandial glucose in our collective was negative, implicating the importance of insulin and triglycerides in early stages of metabolic syndrome when glucose levels are still normal." (PMID 18761738, 2008). "Our data show distinct differences in the prevalence of metabolic syndrome and the level of agreement between the definitions that do not require the measurement of insulin levels and the definitions that do require." (PMID 18088443, 2007). "Surplus subjects classified as metabolic syndrome by IDF but not by WHO definition also had significantly higher fasting insulin levels than subjects without the metabolic syndrome." (PMID 18088443, 2007). "In this hospital based cohort, OSA was shown to be independently associated with the metabolic syndrome (IDF criteria), driven largely by increased serum triglyceride, elevated glucose and day-time sleepiness but not with insulin resistance state." (PMID 17078884, 2006). "Improvements were found in all three indices of glucose and insulin metabolism- FPG, OGTT and HbA1c suggesting that Telmisartan may be effective in reducing the progression of metabolic syndrome." (PMID 15892894, 2005). "Furthermore, Cyp17a1 KO rats did not exhibit the rise in plasma insulin concentration that is frequently seen in patients with metabolic syndrome, even when they were given a high-fat diet." (PMID 41385510, 2025).
metabolic syndrome (continued). "Individuals with MDD or bipolar disorder (BD) may vary widely in terms of insulin sensitivity, inflammatory status, and body composition, even in the absence of clinical metabolic syndrome." (PMID 41010364, 2025). "The SAF values significantly differed between the groups with and without hypertension (p = 0.003), dyslipidemia (p = 0.035), macroangiopathy (p = 0.005), neuropathy (p = 0.008), diet therapy (p = 0.001), insulin use (p = 0.021), diuretic use (p = 0.024), and diabetic retinopathy stage (p = 0.013)." (PMID 41381649, 2025). "The argument that pigs may be too young to exhibit fasting metabolic syndrome biomarkers is also supported by nonsignificant plasma fasting glucose and insulin concentrations in experimental groups compared to the TPN-control group." (PMID 40441384, 2025). "Peripheral and hepatic insulin sensitivity improved only in lean individuals and not in individuals with metabolic syndrome, suggesting a potential difference in SCFA regulation of glucose metabolism between healthy individuals and individuals with metabolic syndrome." (PMID 40557239, 2025). "Therefore, this study aims to assess the effects of PM2.5 exposure on metabolic and hormonal parameters, specifically insulin, adiponectin, leptin, and HOMA-IR, by comparing healthy individuals and individuals with metabolic syndrome across two distinct PM2.5 seasons in Chiang Mai, Thailand." (PMID 40863890, 2025). "Similarly, another meta‐analysis among participants with metabolic syndrome did not identify any beneficial effects for LCDs on inflammation while this type of diet had an effect on lowering insulin and body weight." (PMID 40688603, 2025). "Additionally, a negative correlation was identified between fasting blood insulin levels and metabolic syndrome and serum carotenoid (lycopene, lutein, and β-carotene) concentrations." (PMID 39940428, 2025). "In the subsample of 1779 patients, greater BMI and LDL, and non-use of insulin were associated factors for cardiovascular disease patterns; older age, higher HDL, lower LDL, and insulin use for dyslipidemia patterns; male sex, higher TG and LDL, and non-use of insulin for hypertension patterns." (PMID 40084007, 2025). "Since metabolic syndrome markers like fasting blood sugar, triglyceride-to-high-density lipoprotein ratio, and insulin-to-BMI ratio were not available for all 80 patients, the potential association with biomarkers of the ATN profile was analyzed in smaller subsets." (PMID 40125215, 2025). "Moreover, the extract improved dyslipidemia (reduced total and LDL-cholesterol, reduced triglycerides, increased HDL-cholesterol), suggesting its capacity to reduce lipid efflux mechanisms and improve insulin signaling." (PMID 41237113, 2025). "Consequently, PON1 may offer protection against conditions like diabetes, metabolic syndrome, cardiovascular disease, and PCOS that have decreased insulin levels." (PMID 38982395, 2024). "With regard to the use of drugs related to metabolic syndrome, 26 women (46.4%) were taking an antihypertensive, 32 (57.1%) a hypolipemic agent, 6 women (10.7%) a drug against hypertriglyceridemia, 6 women (10.7%) an oral antidiabetic (OAD), and 1 was undergoing insulin therapy." (PMID 39597078, 2024). "With respect to other metabolic syndrome biomarkers, the nonsignificant fasting plasma glucose and insulin concentrations suggest that our pigs may have been too young to exhibit any fasting biomarkers of metabolic syndrome." (PMID 39270853, 2024). "Additionally, sodium butyrate supplementation (4 g/day) enhances insulin sensitivity solely in lean individuals and not in those with metabolic syndrome." (PMID 38792581, 2024). "Moreover, the study did not exclude individuals using insulin or lipid-lowering medications, a factor of significance given the substantial number of diabetic and metabolic syndrome patients." (PMID 39765929, 2024).
metabolic syndrome (continued). "This study aimed to investigate whether a reduction in daily sedentary behavior (SB) improves insulin sensitivity in adults with metabolic syndrome in 6 months, without adding intentional exercise training." (PMID 36251378, 2023). "It indicates that when these drugs are clinically used to treat dyslipidemia, fenofibrate may increase insulin secretion while pemafibrate has no such effect." (PMID 37697384, 2023). "And the lack of data on plasma insulin that could drive dyslipidemia or NAFLD may influencing the presented data." (PMID 37214248, 2023). "Furthermore, IL-1β concentrations did not correlate significantly with clinical parameters of metabolic syndrome, except for insulin sensitivity/resistance (insulin level and HOMA-IR index)." (PMID 37703108, 2023). "In obese humans and Metabolic Syndrome (MetS) patients, circulating CTRP7 levels were significantly elevated and positively correlated with BMI, glucose, insulin, insulin resistance index, hemoglobin A1c, and triglyceride levels, which may be a novel biomarker related to metabolic diseases." (PMID 37901246, 2023). "This review discusses how the Western diet and lifestyle (Westernization) has played an important etiological role in the pathogenesis of the metabolic syndrome and its consequences by exerting negative effects on activity of the insulin–insulin-like growth factor-I (insulin–IGF-I) system." (PMID 36901984, 2023). "For instance, in a diet-streptozotocin rat model, Sargassum polycystum extracts decreased the fasting plasma glucose, reduced dyslipidemia, and ameliorated the oxidative stress without altering the insulin levels, suggesting an improvement in the insulin sensitivity." (PMID 37047820, 2023). "Among various components of metabolic syndrome, PA (but neither insulin + high glucose nor UA per se) is a major positive regulator of URAT1 expression, at least in cardiomyocytes, and a primary factor that causes a sequence of pathological findings in the diet-induced metabolic heart." (PMID 37694143, 2023). "This study demonstrated that the probiotic preparation improved liver function and dyslipidemia in a healthy population with NADLD and significantly improved hepatocyte steatosis, possibly by regulating the intestinal flora and thereby reducing inflammatory factors and improving insulin resistance." (PMID 35936368, 2022). "Indeed, according to the literature, impaired insulin sensitivity is a more variable and non-systematic physiological disturbance in the study of metabolic syndrome in Wistar rats." (PMID 35807489, 2022). "A recent study of 24 participants with metabolic syndrome administered a single-strain probiotic of Anaerobutyricum soehngenii, with limited evidence of improvements in insulin sensitivity and no detected increases in fecal SCFAs (circulating SCFAs were not measured)." (PMID 34996347, 2022). "Our study findings indicate that though insulin was able to maintain the glycemic control and ameliorate dyslipidemia, it could not decrease the oxidative stress to the same extent." (PMID 33449943, 2021). "The analyzed population showed similar levels of glucose, insulin, homeostasis model of assessment-insulin resistance (HOMA-IR), low-density lipoprotein cholesterol (LDL-C), and triglycerides as the controls, but the incidence of metabolic syndrome was significantly increased." (PMID 33716979, 2021). "Lower expression of PPARγ is linked to the pathogenesis of metabolic syndrome, whereas increased OXPHOS have been associated to increased basal respiration and oxidative stress a characteristic of adipocytes from insulin resistant obese-nondiabetic humans and mice." (PMID 33924880, 2021).
metabolic syndrome (continued). "Accumulating evidence suggests that IGF-BP1 and IGF-BP2 may increase insulin sensitivity directly and cluster with components of the metabolic syndrome in obese children Hence, these IGF-BPs may serve as a useful biomarker of insulin sensitivity in early childhood." (PMID 33915788, 2021). "However, the inability to properly respond to insulin is related to endothelial dysfunction as well as arterial stiffness, which likely contribute to the development of CVD, atherosclerosis, T2DM, and metabolic syndrome (MetS)." (PMID 34069950, 2021). "This has a significant implication for dietary strategy, as diets which are beneficial for metabolic syndrome and promote insulin signaling, even while not ketogenic, may confer a significant advantage." (PMID 34235637, 2021). "In this study, we revealed for the first time that direct inhibition of CCL4 could reverse the impaired insulin signaling pathway by decreasing the phosphorylation of IRS-1 in skeletal muscle and liver tissues in mice with both type 2 DM and metabolic syndrome." (PMID 33968046, 2021). "Our results indicated that at the age of 24 weeks, MSG-IO mice showed apparent metabolic syndrome appearances; increased body weight, body weight gain, waist circumference, and LEE index; and significant increases in fasting blood glucose and serum insulin levels and HOMA-IR index." (PMID 32090078, 2020). "According to this scenario, the lower body fat mass, the higher insulin sensitivity, the lower fatty acid accumulation on liver, and finally, the input of n-3 PUFA anti-inflammation of goat’s milk prevented the establishment of metabolic syndrome in our mice as showed our results." (PMID 32752280, 2020). "In addition, the association between hepatic fibrosis and risk of atherosclerosis progression was significant in all metabolic subgroups regardless of age, BMI, presence of metabolic syndrome, or insulin sensitivity." (PMID 32534588, 2020). "Similarly, in the group with PreDM the subgroup with low IGFBP-1 levels (n = 32) at baseline had signs of the metabolic syndrome with decreased HDL and adiponectin as well as increased triglycerides, insulin, HOMA-IR and IGFSD compared to the subgroup with high IGFBP-1 (n = 13)." (PMID 32934313, 2020). "Resveratrol 150 mg/d for 6 mo had no beneficial effect on insulin sensitivity, assessed by the Matsuda index, nor on outcome parameters related to liver fat accumulation, body composition, dyslipidemia, energy metabolism, physical performance, and quality of life and sleep, compared with placebo." (PMID 32492138, 2020). "However, supplementation with sodium butyrate for 1 month did not alter hepatic or peripheral insulin sensitivity in men with the metabolic syndrome." (PMID 32880688, 2020). "The association between dyslipidemia with IGM rather than subtle GC excess suggests that GC may indirectly affect lipid metabolism by mediating glucose metabolism and insulin resistance." (PMID 33633684, 2020). "Since fasting blood glucose measurements were not obtained in the HUNT study, nor was any other measure of insulin resistance, our definition of the metabolic syndrome was based on the available data on waist circumference, blood pressure and blood lipids only." (PMID 31892102, 2019). "However, insulin dose and the metabolic syndrome were not good predictors in a study with DD patients." (PMID 31685799, 2019). "Therefore, participants in the present study had to be lean and insulin-sensitive (evaluated as HOMA-IR < 1.7) with no features of metabolic syndrome." (PMID 31540317, 2019). "The insulin-sensitizing effect of CYC27 might have an important role in the improvement of glucose levels and dyslipidemia in diabetic BKS db mice because this pathway had been implicated in glucose transport in muscle and lipid metabolism for liver and adipose tissues." (PMID 30641913, 2019).
metabolic syndrome (continued). "We concluded that decreased level of obestatin may contribute to the development of metabolic syndrome and altered lipoprotein metabolism in obese patients even without disturbed insulin sensitivity." (PMID 29506551, 2018). "Evidence also showed that rs3856806 in PPARγ had a close relationship with metabolic syndrome, subjects with TT genotype had higher BMI in males, and those with TT/TC genotypes had higher systolic blood pressure, HOMA-IR, and larger body fat percentage, which were all related to insulin sensitivity." (PMID 29849618, 2018). "Moreover, in accordance with several reports, our study also observed negative correlation of SHBG with metabolic syndrome factors (BMI, waist circumference, and TG) and diabetic parameters (insulin and HOMA-IR), which is in line with previous studies." (PMID 30057912, 2018). "Of note, 7 days of fructose overload are enough to induce autonomic dysfunction of baroreflex control of cardiovascular regulation in this experimental model of metabolic syndrome even without inducing any alteration in the metabolic profile (triglycerides, glucose, insulin and insulin resistance)." (PMID 29872081, 2018). "Similarly 14 weeks on a HFD leads to the early stage of metabolic syndrome in male but not female mice, including hyperinsulinemia, higher blood glucose, and insulin tolerance." (PMID 29718979, 2018). "Although the obtained results are interesting regarding the potential treatment of patients with the metabolic syndrome, authors have recognized the following limitation of the conducted studies:The insulin levels were not determined at the end of the experiment." (PMID 29110282, 2018). "Furthermore, K-111 exhibits various pharmacological therapies for insulin sensitivity, dyslipidemia and hypertension in a nonhuman primate model." (PMID 30060458, 2018). "The significant lower insulin concentration observed after intake of MPH could be important in patients with reduced insulin sensitivity, thus should be further investigated in a group of patients with the metabolic syndrome and/or T2DM." (PMID 30524707, 2018). "Fructose supplementation did not decrease whole-body insulin-mediated glucose transport, corresponding mainly to muscle insulin sensitivity with the exception of one study performed in middle-aged subjects with metabolic syndrome." (PMID 30060614, 2018). "The lack of a dosage-based phenotype for glucose and insulin tolerance may be attributed to simply avoiding the age-related metabolic syndrome that is observed in wild type mice, due to their leanness, rather than substantial changes to insulin signaling." (PMID 30213134, 2018). "Therefore, downregulation of glucose and insulin levels by MLE may, at least in part, be responsible for the improvement of dyslipidemia and fatty liver in db/db mice." (PMID 30150922, 2018). "However, short-term fish oil supplementation could improve insulin sensitivity among patients with metabolic disorders, which could be a significant intervention as secondary prevention for the T2DM and metabolic syndrome." (PMID 28673352, 2017). "Finally, our study did not measure other cardio-metabolic biomarkers such as blood glucose, insulin, lipids, triglycerides and C-peptide, and thus lacking outcomes such as dysglycemia or dyslipidemia." (PMID 28827610, 2017). "Our findings suggest that a short-term elevation in EPI with correspondingly higher branched chain amino acid (BCAA) contents has no detrimental impact on hepatic and peripheral insulin sensitivity or plasma lipid parameters in older adults with metabolic syndrome." (PMID 28713581, 2017). "Moreover, IR is critically involved in the development of metabolic syndrome and cardiovascular disease in PCOS women, that is why its treatment (lifestyle changes, insulin-sensitizing drugs and bariatric surgery) is thought to important both to decrease IR and to alleviate its consequences." (PMID 27473078, 2017).